ALK (ALK receptor tyrosine kinase)
Diseases named in the same sentence as ALK in open-access papers (continued):
Sharing a sentence is not in itself a finding about the gene and the disease.
sarcomatoid carcinoma (12 papers, 2013 to 2026). A malignant epithelial neoplasm characterized by the presence of spindle cells and anaplastic morphologic features. "This case illustrates the compounding diagnostic pitfalls of oral IMT: dual-site involvement, two failed biopsies, ALK negativity in an elderly patient, and focal cytokeratin positivity risking misclassification as spindle cell carcinoma." (PMID 42266280, 2026). "Presence of ALK gene rearrangements in sarcomatoid carcinoma has significant therapeutic implications and potential for altering the prognosis of this fatal disease." (PMID 32149365, 2020). "Eight sarcomatoid carcinoma were analyzed for the presence of EGFR kinase domain mutations, KRAS mutations, HER2 kinase domain mutations, BRAF mutations, ALK fusions, RET fusions and AKT1 mutations." (PMID 26486077, 2015). "Of the 20 ALK-positive cases, 19 (95%) were adenocarcinomas, and 1 was sarcomatoid carcinoma which had a significant spindle cell and giant cell component." (PMID 23741400, 2013). "Histologically, almost all the ALK-rearranged cases were adenocarcinoma, except that one case was sarcomatoid carcinoma." (PMID 23741400, 2013). "Unlike IMT, previous studies have shown that sarcomatoid carcinomas do not express ALK on immunohistochemistry, but further investigation is needed to confirm these findings." (PMID 27293951, 2016).
cholangiocarcinoma (11 papers, 2016 to 2025). A carcinoma that arises from the intrahepatic biliary tree (intrahepatic cholangiocarcinoma) or from the junction, or adjacent to the junction, of the right and left hepatic ducts (hilar cholangiocarcinoma). "Using CCA cell lines and close-to-patient primary cholangiocarcinoma cells, we investigated the potential for ALK inhibitors in CCA." (PMID 38144528, 2023). "Initiation of clinical trials with ceritinib in CCA patients, irrespective of their ALK mutation status, with retrospective analysis on the clinical responses, is warranted to fully unlock ceritinib’s therapeutic potential in cholangiocarcinoma." (PMID 38399413, 2024). "The purpose of this study was to gain further insight into the relationship and interplay between the expression of ALK, cMet, and ROS1 and the cytotoxicity of crizotinib, ceritinib, and capmatinib in cholangiocarcinoma cells." (PMID 38144528, 2023).
Hypercholesterolemia (11 papers, 2019 to 2025). An increased concentration of cholesterol in the blood. "Hypercholesterolemia and hypertriglyceridemia represented the most common treatment-related AEs, and the antitumor activity of lorlatinib was seen across a range of ALK resistance mutations, including G1202R." (PMID 33171712, 2020). "However, inhibiting ALK-Aug signaling to treat obesity may pose a challenge, as small molecular inhibitors of ALK that penetrate the blood–brain barrier can lead to weight gain, hypertriglyceridemia, hypercholesterolemia, and hypertension." (PMID 37892172, 2023). "Unlike other ALK inhibitors for which the main side effects were hepatotoxicity and gastrointestinal upset, common adverse effects of lorlatinib included hypercholesterolemia (72%), hypertriglyceridemia (39%), peripheral neuropathy (39%), and peripheral edema (39%)." (PMID 30975211, 2019).
inflammatory breast carcinoma (11 papers, 2013 to 2025). An advanced, invasive breast adenocarcinoma characterized by the presence of distinct changes in the overlying skin. "Authors extended their study to clinical tumor samples of inflammatory breast cancer and detected ALK copy number gains and gene amplification in 20/25 (80 %) patient tumor samples." (PMID 26312204, 2015). "HCNGs of ALK were limited to a subset of inflammatory breast cancer (3, 23 %), and a single ER−/PR−/HER2+ (1, 7 %) case." (PMID 26312204, 2015). "Since the previous studies on ALK are primarily focused on inflammatory breast carcinoma, we analyzed the results of our 13 inflammatory breast carcinoma cases separately." (PMID 26312204, 2015). "A recent report described a possible role for ALK amplification in inflammatory breast cancer (IBC)." (PMID 24156086, 2013). "In our study, none of the 13 inflammatory breast cancer cases (including 3 cases with high CNG) exhibited ALK protein overexpression by immunohistochemistry." (PMID 26312204, 2015).
metastatic melanoma (11 papers, 2014 to 2026). A melanoma that has spread from its primary site to another anatomic site. "Here, we report a CBX3::ALK out-of-frame fusion identified in a case of metastatic melanoma, which produces functional ALK isoforms via alternative translation start sites." (PMID 41887222, 2026). "More recently, a novel isoform of ALK has been described in a subset of primary and metastatic melanomas." (PMID 28895885, 2017). "However, metastatic melanoma patients treated with double immune checkpoint inhibition and metastatic NSCLC patients treated with anaplastic lymphoma kinase (ALK)-targeting tyrosine kinase inhibitors (TKIs) are today achieving median OS beyond 3–5 years." (PMID 34717664, 2021). "To broaden the scope of our findings and to better understand if the proposed drug combination could be of clinical relevance for patients, we examined the presence of ALK in 26 FFPE samples derived from both primary and metastatic melanoma patients." (PMID 30290811, 2018).
NK/T-cell lymphoma (11 papers, 2014 to 2025). "Most patients treated with A + CHP had sALCL (ALK+ and ALK−, 51%), PTCL-NOS (30%), or AITL (12%); in contrast, most patients treated with CHOP had PTCL-NOS (51%), AITL (19%), sALCL (ALK + and ALK–, 10%), or mature T/NK-cell lymphoma (8%)." (PMID 36971492, 2023). "Of 102 patients enrolled, 41 had PTCL-NOS, 23 had NK/T cell lymphoma, 12 had ALK-ALCL, 7 had ALK + ALCL, and 19 had other PTCL subtypes." (PMID 36959853, 2023). "Among T/NK cell lymphomas, 38.8% were ATLL, 25.7.8% were AITL, 16.8% were PTCL‐NOS, and 6.2% were ALCL (2.2% ALK+ and 4.0% ALK−)." (PMID 30311404, 2018). "In patients with EN NK/T-cell lymphoma and ALK-negative ALCL, transplantation also improved OS." (PMID 40839148, 2025). "According to the WHO classification, 107 (42.1%) patients had PTCL-NOS, 54 (21.3%) had extranodal NK/T-cell lymphoma, 48 (18.9%) had AITL, and 28 (11.0%) had ALK-negative ALCL in the auto-SCT group." (PMID 37365207, 2023).
osteosarcoma (11 papers, 2017 to 2025). A usually aggressive malignant bone-forming mesenchymal neoplasm, predominantly affecting adolescents and young adults. "Due to the identification of an alternative transcript (ATI) on ALK, the patient with osteosarcoma underwent a targeted therapy with the ALK-inhibitor crizotinib, which would likely not have been identified in our in-house panel testing." (PMID 37542550, 2023). "Microscopically, tumor cells appeared spindled-pleomorphic and showed diffuse strong ALK immunoreactivity, consistent with ALK-rearranged high-grade osteosarcoma." (PMID 38096470, 2023). "The resected RML metastasis, the first tumor where we detected the ALK rearrangement, was morphologically distinct (ie, an absence of osteoid formation) from the previous tumors, including an earlier lung metastasis with typical osteosarcoma morphology." (PMID 38096470, 2023). "Herein, we report a 73-year-old man with an acquired ALK-rearranged osteosarcoma." (PMID 38096470, 2023). "Here, to our knowledge, we document the first known acquired ALK rearrangement in osteosarcoma." (PMID 38096470, 2023). "The several novel variants of ALK, BLM, PTCH1 in this patient might expand the mutational spectrums of the osteosarcoma." (PMID 35057767, 2022).
spindle cell neoplasm (11 papers, 2014 to 2025). A benign or malignant neoplasm characterized by the presence of neoplastic spindle cells. "IMT is a low-grade spindle cell neoplasm typically associated with anaplastic lymphoma kinase (ALK) and more rarely with ROS oncoprotein (ROS1) or neurotrophic tropomyosin kinase receptor (NTRK) rearrangements and a less aggressive clinical course compared to DDLPS." (PMID 40211332, 2025). "The presented case highlights a predominantly spindle cell variant of EFH and suggests inclusion within the recently described myxoid spindle cell EFH spectrum, which encompasses the superficial ALK-rearranged myxoid spindle cell neoplasms (SAMS)." (PMID 40688914, 2025). "Recently, a new ALK-rearranged spindle cell tumor has been described in a cohort of four children aged 2 to 10 years." (PMID 35565289, 2022). "ALK immunostaining is an aid in the pathological diagnosis of IMTs, as well as in the differentiation of IMTs from other spindle cell neoplasms that fall within the broad category of IPTs." (PMID 27846861, 2016). "Other PK-related neoplasms in the differential diagnoses are the plaque-like stage of dermatofibrosarcoma protuberans (DFSP) and the ALK-rearranged CD34-positive spindle cell neoplasm/medallion-like dendrocyte hamartoma/plaque-like CD34-positive dermal fibroma." (PMID 40387903, 2025). "Molecular exploration of ALK rearrangements and KIT mutations may be required to diagnose KIT-positive spindle cell tumors." (PMID 24938355, 2014). "Histologically, a spindle cell tumor that was immunohistochemically positive for both KIT and ALK was also identified." (PMID 24938355, 2014). "However, detection of an ETV6–NTRK3 fusion supported classification as an ALK‐negative IMT rather than an IPT or another spindle cell neoplasm." (PMID 41368177, 2025). "However, more evidence is required to rule out a GIST, even if a spindle cell tumor is positive for ALK." (PMID 24938355, 2014). "However, the diagnosis of ALK-negative spindle cell neoplasm with inflammation could be a significant challenge, especially, when tumors arose in older patients or at unusual anatomic sites, or tumors showed atypical spindle cells." (PMID 37735390, 2023).
bone metastasis (10 papers, 2017 to 2025). Transfer of a neoplasm from its primary site to bones. "In ALK‐positive patients, we found significant associations between poor PS and bone metastasis with CYFRA 21‐1 levels." (PMID 38400801, 2024). "ALK mutation tests were performed in 19 cases and the mutation rate of bone metastasis was 31.6 % (6/19)." (PMID 27444682, 2017). "Ceritinib is used for the treatment of patients with anaplastic lymphoma kinase (ALK)-rearranged non-small cell lung cancer (NSCLC), who are at the risk of developing bone metastasis." (PMID 36425467, 2022). "What we found was that both ALK‐positive patients and ALK‐negative patients had similar occurrence of bone metastasis in the course of disease." (PMID 28374971, 2017). "The results remind clinicians that a whole‐process management of bone metastasis should be applied into ALK‐positive patients." (PMID 28374971, 2017). "Among them, 12 (9.4%) were over 65 years of age, 67 (52.3%) were women, 33 (25.8%) had a smoking history, 50 (39.1%) had bone metastasis at baseline, 79 (61.7%) received at least one cycle of chemotherapy before crizotinib treatment, and 19 patients (14.8%) received three or more ALK‐TKI treatments." (PMID 35560808, 2022). "Based on the results that ALK‐positive patients were inclined to have brain and bone metastasis, we hypothesized that ALK‐positive patients tended to form distant metastasis through hematogenous spread, while both ALK‐ and EGFR‐negative patients tended to invade local region by lymphatic vessels." (PMID 28374971, 2017). "Univariate analysis showed that patients age <65 years, without bone metastasis at baseline, and undergoing next‐generation ALK inhibitors had longer OS than other patients." (PMID 35560808, 2022).
mantle cell lymphoma (10 papers, 2013 to 2022). Mantle cell lymphoma is a rare form of malignant non-Hodgkin lymphoma affecting B lymphocytes in the lymph nodes in a region called the ``mantle zone''. "SP53, a mantle cell lymphoma cell line, served as the negative control for ALK and pALK." (PMID 27641368, 2016). "In addition, two anaplastic lymphoma kinase (ALK)-positive ALCLs, one ALK-negative ALCL, and one mantle cell lymphoma (MCL) were identified." (PMID 29029457, 2017).
medullary thyroid cancer (10 papers, 2015 to 2026). "ALK fusions have also been descried in medullary thyroid cancer (EML4-ALK and Glutamine:fructose-6-phosphate transaminase 1 (GFPT1)-ALK), with patient response to crizotinib reported in an EML4-ALK patient." (PMID 28030793, 2017). "ALK fusion has been demonstrated in medullary thyroid cancer and anaplastic carcinoma." (PMID 31533238, 2019). "The approvals based on early phase studies regarded especially targeted therapy (anti ROS1, anti ALK, and anti-RET) in NSCLC and some rare disease (medullary and non-medullary thyroid cancer, soft tissue sarcoma, GIST)." (PMID 35205637, 2022).
neuroendocrine carcinoma (10 papers, 2021 to 2025). A malignant neuroendocrine neoplasm composed of cells containing secretory granules that stain positive for NSE and chromogranin. "It is worth noting that some cases of ARMS can also express Syn, CD56, AE1/AE3, and ALK, which makes it necessary to distinguish ARMS from small cell carcinomas and neuroendocrine carcinomas." (PMID 38835374, 2024). "Recognition of these findings should help to avoid misinterpretation as SEF, ALK-rearranged RCC, and neuroendocrine carcinoma." (PMID 34228212, 2022).
pneumonitis (10 papers, 2018 to 2025). An inflammatory process affecting the lung parenchyma. "In a retrospective analysis of 250 patients with ALK TKI-related pneumonitis, smoking history increased the risk of pneumonitis 3.61-fold." (PMID 40342820, 2025). "The risk factors for high-grade pneumonitis after ALK TKI use include prior smoking history, concomitant medications, older age (>64 years), and renal dysfunction (creatinine clearance <80 ml/min)." (PMID 40342820, 2025). "Timely diagnosis and early treatment of pneumonitis caused by ALK-TIs are key to improving the prognosis of these patients." (PMID 39834688, 2025). "Alectinib is also generally associated with a lower incidence of pneumonitis among all ALK TKIs, a priority for our patient who had a significant pulmonary adverse event after brigatinib administration." (PMID 40342820, 2025). "We present a patient with echinoderm microtubule-associated protein-like 4 (EML4) and ALK fusion protein-positive mNSCLC who developed severe hypoxemia and pneumonitis requiring intubation within 2 days of initiating brigatinib therapy." (PMID 40342820, 2025). "All ALK TKIs present pneumonitis and lung opacities, but alectinib was associated with more PTs than acute eosinophilic pneumonia, and lung infiltration was not shown with other inhibitors." (PMID 39399468, 2024). "Our study has revealed for the first time that the lowest rate of all‐grade and high‐grade pneumonitis is associated with lorlatinib compared with other ALK TKIs." (PMID 37017467, 2023). "The findings of this meta‐analysis reveal an association between the occurrence of pneumonitis and use of ALK TKIs." (PMID 37017467, 2023). "Timely diagnosis and early treatment of pneumonitis caused by ALK‐TKIs are key to improving the prognosis of these patients." (PMID 37017467, 2023). "The mechanism underlying the development of ALK‐induced pneumonitis is yet to be fully elucidated; however, alveolar epithelial injury is thought to play a role." (PMID 37017467, 2023). "Further research is needed to determine whether re‐challenging with ALK TKIs carries an increased risk of recurrent pneumonitis." (PMID 37017467, 2023). "Pneumonitis associated with ALK TKIs can be considered as allergic pneumonitis." (PMID 37017467, 2023). "On comparing different second‐generation ALK TKIs, patients who were administered brigatinib (3.06%, 95% CI: 1.28%–5.41%) had a higher risk of high‐grade pneumonitis than those administered ceritinib (1.18%, 95% CI: 0.15%–2.80%) and alectinib (1.22%, 95% CI: 0.16%–2.98%)." (PMID 37017467, 2023). "Hence, before receiving treatment with ALK TKIs, patients with a history of chemotherapy should undergo stricter screening in order to decrease the risk of pneumonitis and prevent fatal pneumonitis." (PMID 37017467, 2023). "In this meta‐analysis, we aimed to determine the incidence of ALK‐TKI‐associated pneumonitis." (PMID 37017467, 2023). "In the OAK study, patients baseline characteristics include more EGFR KRAS mutation positive and ALK fusion positive patients, those patients who receive previous treatment with tyrosine kinase inhibitor are more likely to experience pneumonitis and lung inflammation." (PMID 30618738, 2018). "Future research directions could include prospective studies to better characterize the incidence, risk factors, and underlying mechanisms of ALK TKI-induced pneumonitis, along with the development of predictive biomarkers to identify patients at higher risk of developing pulmonary toxicity." (PMID 40342820, 2025). "A Limited number of previous case reports have described the successful of crizotinib, ceritinib, alectinib or brigatinib in patients with ALK-rearranged NSCLC who have recovered from pneumonitis secondary to ALK-TKIs." (PMID 39834688, 2025).